SNORA50B (small nucleolar RNA, H/ACA box 50B)
Gene: Small nucleolar RNA gene on chromosome 22 (33,704,786 to 33,704,920, reverse strand). Ensembl gene ENSG00000253007.
Gene Ontology:
Biological process: RNA processing
Cellular component: nucleolus
Homologues: Orthologues: chimpanzee SNORA50B (100% identical), macaque SNORA50B (98% identical), pig SNORA50B (83% identical), rabbit SNORA50B (77% identical). Paralogues in human: SNORA50A (62% identical), SNORA50D (59% identical), SNORA50C (57% identical).